IL15 (interleukin 15)
Diseases named in the same sentence as IL15 in open-access papers (continued):
Sharing a sentence is not in itself a finding about the gene and the disease.
myocardial infarction (9 papers, 2014 to 2025). Gross necrosis of the myocardium, as a result of interruption of the blood supply to the area, as in coronary thrombosis. "IL-15 levels are elevated in some cardiovascular diseases, such as myocardial infarction and atherosclerosis." (PMID 37047399, 2023). "At the same time, there is evidence demonstrating that IL-15 has a protective effect in myocardial infarction and myocarditis, reducing the death of cardiomyocytes." (PMID 37047399, 2023). "In a mouse model of myocardial infarction, the administration of IL15 improved cell death and LV function." (PMID 35964012, 2022). "Furthermore, IL-15 is also involved in the pathophysiology of other cardiovascular diseases (CVDs) such as atrial fibrillation, myocardial infarction and myocarditis." (PMID 35783134, 2022). "Furthermore, IL‐15 has a protective effect in myocardial infarction and myocarditis by decreasing cardiomyocyte death and improving heart function." (PMID 32406586, 2020). "It suggests that IL‐15 plays a positive role in myocardial infarction." (PMID 32406586, 2020). "Moreover, administration of IL‐15 could improve heart function of C57/B6 mouse after myocardial infarction by reducing cardiomyocyte death." (PMID 32406586, 2020).
schizophrenia (9 papers, 2013 to 2025). A major psychotic disorder characterized by abnormalities in the perception or expression of reality. "Elevations of IL-15 levels have also been reported in patients with schizophrenia, which is interesting in light of the possible genetic overlaps between AN and schizophrenia that have been identified in genome-wide association study (GWAS) data." (PMID 30355978, 2018). "Consistently, several studies found that the IL-15, IL-16, and IL-8 levels in patients with schizophrenia are associated with a poor response to antipsychotic treatment, and increased IL-8 levels are significantly associated with more severe psychiatric symptoms in patients." (PMID 37270510, 2023). "Among pro-inflammatory cytokines, the levels of interleukin (IL)-1α, IL-6, IL-11, IL-12A, IL-15, IL-17A, and granulocyte colony-stimulating factor (G-CSF) in tears were elevated in the schizophrenia group (all P < 0.01)." (PMID 35223927, 2022). "As the ligand of IL-15Rα, IL-15 is a cytokine especially poised to have a pivotal role in CNS organization, and it also has been reported to be a biomarker of schizophrenia and depression." (PMID 35356722, 2022). "Among pro-inflammatory cytokines, the levels of interleukin (IL)-1α, IL-6, IL-11, IL-12A, IL-15, IL-17A, and granulocyte colony-stimulating factor (G-CSF) in tears were significantly higher in patients with schizophrenia than that in normal controls (all P < 0.01)." (PMID 35223927, 2022). "We found higher TGF-α (p = 0.014), IFN-γ (p = 0.036), IL-5 (p < 0.001), IL-6 (p = 0.047), IL-8 (p = 0.005), IL-10 (p <0.001), IL-15 (p = 0.007), IL-1RA (p = 0.007), and TNF-α (p < 0.001) levels in patients with schizophrenia than in healthy individuals." (PMID 36556337, 2022). "We found higher TGF-α (p = 0.014), IFN-γ (p = 0.036), IL-5 (p < 0.001), IL-6 (p = 0.047), IL-8 (p = 0.005), IL-10 (p < 0.001), IL-15 (p = 0.007), IL-1RA (p = 0.007), and TNF-α (p < 0.001) levels in patients with schizophrenia compared with healthy individuals." (PMID 36556337, 2022). "In this work, we found significantly higher serum levels of proinflammatory (IFN-γ, IL-5, IL-6, IL-8, IL-15, and TNF-α) and anti-inflammatory (TGF-α, IL-10, and IL-1RA) cytokines in patients with schizophrenia than in healthy individuals." (PMID 36556337, 2022). "Conversely, other immunoactive molecules, such as α1-antitrypsin, B-lymphocyte chemoattractant, and IL-15, are negatively correlated with schizophrenia symptoms, both positive and negative, as measured by the Positive and Negative Symptom Scale for Schizophrenia (PANSS) scale." (PMID 41010622, 2025).
Stroke (9 papers, 2017 to 2026). Sudden impairment of blood flow to a part of the brain due to occlusion or rupture of an artery to the brain. "A significant decrease (p<0.05) in brain IL-15 levels was seen in the MCAo rGDF11 treated mice at day 10 post-stroke suggesting that rGDF11 reduced brain inflammation." (PMID 32365331, 2020). "IL-15 expression is increased in astrocytes and microglia after injury and worsens functional outcomes after stroke." (PMID 32365331, 2020). "In this sense, IL-15 should play a protective role against stroke or its dependent effects, as likely as further cytokines such as IL-19 or IL-33." (PMID 28373915, 2017). "A decrease in brain IL-15 and IL-18 levels at day 10 along with reduced gliosis at day 30-post stroke could partially explain the protective role of GDF11." (PMID 32365331, 2020). "In our study, the salivary concentration of IL-2, IL-5, IL-7, IL-10, IL-12 (p70), IL-13, IL-15, and IFN-α2 was below the detection level in healthy controls (most commonly) and in stroke patients." (PMID 40520895, 2025). "Here, we also found that levels of IL-1β, IL-1RA, IL-10, IL-13, IL-15, Flt-3L, Fractalkine, EGF, G-CSF and GM-CSF were lower in the severe stroke group." (PMID 31164999, 2019). "Astrocyte-derived IL-15 aggravated cerebral ischemic injury through their activation of neurotoxic CD8+ T and natural killer (NK) cells, neutralizing IL-15-attenuated brain injury and promoting recovery in stroke mice." (PMID 33042113, 2020). "Although there seems to be lack of evidence reporting a role of IL-15 in muscle atrophy following stroke, the most recent reports about this cytokine in this field suggest a possible involvement in this mechanism." (PMID 28373915, 2017). "However, there is no clinical data showing a link between IL-15 and stroke." (PMID 31164999, 2019).
acute hepatitis A (8 papers, 2012 to 2024). "Moreover, the levels of IL-15 were associated with bystander activation of CD8+ T cells in the case of acute hepatitis A patients." (PMID 36590594, 2022). "During acute hepatitis A, IL-15 upregulates CCR5 chemokine receptor enhancing their requirement for liver parenchyma." (PMID 39669576, 2024). "Recently, it has been reported that in acute hepatitis A patients, NKG2DhighCD8+ T cells induced by IL15 promote damage of liver tissue expressing NKG2D ligands such as MICA and MICB." (PMID 30333822, 2018). "Previously, subcutaneous injection of recombinant IL-15 protected mice against concanavalin A-induced hepatitis." (PMID 23028657, 2012). "Additionally, CCR5 has been reported to be upregulated by IL-15, causing migration of bystander CD8+ T cells to the infection site to mediate enhanced liver injury in acute hepatitis A." (PMID 36951943, 2023). "This may mimic events in vivo in which an inflammatory hepatic cytokine microenvironment, found in hepatitis or cancer, dominated by IL‐1, IL‐2, IL‐6, IL‐12, IL‐15, IL‐18, IFNα, IFNγ, and TNFα/β 38, 39, may lead to the expansion of CD49a+ NK cells." (PMID 28952190, 2018). "Synthetic IL-15 could moderately diminish liver injury in concanavalin A or Fas ligand-induced hepatitis, whereas DC-derived IL-15 enhanced endotoxin shock injury through the liver." (PMID 23028657, 2012). "Natural killer (NK) cells mount an immune response against hepatitis C virus (HCV) infection and can be activated by several cytokines, including interleukin-2 (IL-2), IL-15, and interferon-alpha (IFN-α)." (PMID 35891518, 2022). "In our model of hepatitis induced by 400 mg/kg (lethal dose) of APAP in mice, the 5-day mortality was higher for Il15−/− than WT mice [100% (8/8) vs. 60% (6/10)]." (PMID 23028657, 2012). "Through transcriptional arrest of hepatocytes, GalN with endotoxin or TNFα had been reported to induce acute apoptotic hepatitis in mice, whereas GalN pre-treatment markedly diminished the increased APAP hepatitis in Il15−/− mice versus a minor advantage in WT controls." (PMID 23028657, 2012). "In the case of acute hepatitis A, hepatocytes have also been suggested as the main source of IL-15, but we could not detect it in HEV-3-infected hepatocyte cell line culture." (PMID 33617602, 2021). "However, the GalN reduction effect on APAP hepatitis in WT mice was not as much as that in Il15−/− counterparts." (PMID 23028657, 2012).
co-infection (8 papers, 2011 to 2026). "EBV coinfection intensified this phenotype, being associated with elevated levels of IL-6, IL-10, IL-15, TNF-α, and sCD40L, and with greater loss of memory cell subpopulations." (PMID 41929504, 2026). "At the same time, a drastic decrease in the plasma levels of IFN-γ, TNF-α, Il-1β, IL-15, and IL-17 was detected in patients with HIV/TB coinfection compared to patients with HIV-1 or TB monoinfections." (PMID 37376629, 2023). "Namely, we observed a significant decrease in the production of IFN-γ, TNF-α, IL-1β, IL-15, and IL-17 in patients with HIV/TB coinfection compared to the group of patients with HIV-1 and TB monoinfections." (PMID 37376629, 2023). "In summary, we have shown that patients with HIV-1/TB coinfection are characterized by reduced plasma levels of five proinflammatory cytokines: IFN-γ, TNF-α, Il-1β, IL-15, and IL-17, which are crucial for the control of both infections." (PMID 37376629, 2023). "Co-infection of monocytes with PRRSV-2 strain IAF-Klop and S. suis led to synergistic effects on the expressions of IL-6, CCL5, and TNF-α, and additive effects on productions of CCL4, CCL14, CCL20, IL-15, and PTGS2 (COX-2)." (PMID 38547254, 2024).
Cognitive impairment (8 papers, 2015 to 2025). Abnormal cognition is characterized by deficits in thinking, reasoning, or remembering. "In literature, IL-15 has been shown to be associated with both cognitive impairments and neuropsychiatric symptoms in AD but those results were not convincing." (PMID 25710473, 2015). "To identify biomarkers specific to HF and cognitive impairment, we showed that serum biomarkers for neurodegenerative disease, NfL, and cytokines, IL-6, IL-12p40, IL-15, MIP-1α, TNFα, and TNFβ, levels were significantly higher in HF participants compared to healthy control participants." (PMID 41200931, 2025). "In summary, we have been able to associate serum levels of IL-15 with dementing process of AD as well as non-dementing cognitive impairment." (PMID 25710473, 2015). "IL-15, doing so may contribute to preserving the d related cognitive impairments." (PMID 25710473, 2015). "Interestingly, we found that higher levels of IL-15 in periphery are associated with HAND, though this association was finally lost after correction for possible confounders; similarly, neuroinflammation was associated with cognitive deficits in attention and working memory." (PMID 38704619, 2024). "In other words, elevated IL-15 levels correlate with lesser dementia related cognitive impairment and higher cognitive impairments which are not dementia related." (PMID 25710473, 2015). "A cohort study illustrated that biomarker of neuroinflammation in the CSF such as IL‐6, IL‐15 and MCP‐1 are increased in AD patients with cognitive impairment compared to AD without cognitive impairment." (PMID 39644152, 2024). "Among others, IL-15, CX3CL1 and IL-6 were elevated in patients with minimal HE38, a cognitive impairment we did not assess, but which is likely present in our groups, and the markers could be correlated with both HE and death." (PMID 37973887, 2023).
lung adenocarcinoma (8 papers, 2021 to 2025). A carcinoma that arises from the lung and is characterized by the presence of malignant glandular epithelial cells. "Having demonstrated that cancer cell-intrinsic IL-15 promotes the aggressiveness of cancer cells, we next examined whether tumor cell-specific IL-15 is associated with the progression of lung adenocarcinoma." (PMID 38637902, 2024). "IL-15 was expressed by lung adenocarcinoma cells as determined by immunohistochemistry, and surprisingly, the expression levels of IL-15 in tumors were significantly greater than those in normal lung tissue." (PMID 38637902, 2024). "Gene expression of IL-15 in lung adenocarcinoma, whereas mRNA and protein expression of IL-15 was detected in the Kaplan-Meier and Atlas databases." (PMID 36467072, 2022). "Herein, we investigated the effect of IL-15 on lung adenocarcinoma cells." (PMID 38637902, 2024). "Our results showed that both isoforms of IL-15 were transcribed in lung adenocarcinoma cells, suggesting that the IL-15 produced in tumor cells could be either secreted or stored intracellularly." (PMID 38637902, 2024). "Moreover, IL-15 was also expressed by lung adenocarcinoma cell lines." (PMID 38637902, 2024). "The genes that increased with fivefold following co‐culture with all lung adenocarcinoma cell lines were CD80 (B7‐1), IL‐7, IL‐15, and TNF." (PMID 34907653, 2022). "Specifically, using our TIL-PDX model of human lung adenocarcinoma (TIL-PDX-LUAD), we show profound tumor regression when treated with a combination immunotherapy consisting of IL-15 stimulation and PD-1 blockade." (PMID 34081628, 2021).
preeclampsia (8 papers, 2015 to 2025). Preeclampsia is a hypertensive disorder of pregnancy that is characterized by new-onset hypertension with proteinuria presenting after 20 weeks of gestation, and depending on mild or severe forms may initially present with severe headache, visual disturbances, and hyperreflexia. "First, a genetic deficiency of IL-15 in mice leads to fetal growth restriction, morphologically abnormal deciduae, and impaired remodeling of spiral arteries, a pathologic hallmark of preeclampsia." (PMID 34681751, 2021). "This review emphasizes the substantial contribution of interleukins IL-15, IL-16, IL-17, and IL-35 to the immunopathology of preeclampsia." (PMID 41375625, 2025). "The majority of the published data showed that women with preeclampsia have significantly higher levels of IL-15 and IL-17 in their plasma compared to normotensive women, whereas IL-35 levels were mainly decreased, respectively." (PMID 41375625, 2025). "A strong signature of dysregulated decidual gene expression (e.g., decreased levels of IGFBP1, glycodelin, PRL and IL-15) also emerged among women with severe preeclampsia compared with those experienced normal pregnancies." (PMID 37404833, 2023). "Placental explants from term pregnancies affected by severe preeclampsia produce fourfold less IL-15 in culture than explants prepared from healthy term pregnancies." (PMID 34681751, 2021). "In the uterus of women with preeclampsia, IL15 transcript was upregulated tenfold in DSCs but only twofold in ESFs." (PMID 34681751, 2021). "Serum levels of pro-inflammatory IL-15 and IL-16 are significantly higher in preeclampsia than in normal pregnancy." (PMID 26247971, 2015). "IL-15 was modestly elevated in the serum of women with preeclampsia at term." (PMID 34681751, 2021). "Another example of unrestrained IL-15 is in the BPH/5 mouse, a model of spontaneous hypertension and preeclampsia." (PMID 34681751, 2021). "Later, they found lower levels of HSP70 and interleukin-15 (IL-15) in the meconium of patients with preeclampsia than in those with normal pregnancy and suggested that the downregulation of HSP70 and IL-15 levels supports the retention of pregnancy material in patients with auditory abortion." (PMID 36299775, 2022). "However, IL-15−/− mice neither develop gestational hypertension nor is their progeny growth retarded." (PMID 28670317, 2017).
prostate tumor (8 papers, 2007 to 2023). "Localised administration of a STING agonist together with cyto-IL-15 can confer significant systemic benefits and long-lasting immunity against prostate tumors while reducing immune related toxicities." (PMID 37465665, 2023). "Cyto-IL-15 alone or in combination with cyto-abs, administered intratumorally in subcutaneous prostate tumors in mice, delayed tumor growth and increased survival by expanding the infiltration of NK and CD8+ T cells in the tumors leading to tumor necrosis." (PMID 37465665, 2023). "The in vivo investigation of the efficacy of IL-15 showed that only cytotopically modified IL-15 in doses equal or higher to 5 μg led to both a significant growth delay of TRAMP-C2 prostate tumors and an increase in mice survival compared with control." (PMID 34778376, 2021). "In a previous study carried by our laboratory, the efficacy of a membrane-localizing cytotopically modified IL-15 to treat prostate tumors in vivo was examined." (PMID 34778376, 2021). "The injection of cytotopically modified IL-15 intratumorally in prostate tumors has been proven successful in the reduction of tumor size and in prolonging mice survival." (PMID 34778376, 2021). "The efficacy of cyto-IL-15 was investigated in subcutaneous TRAMP-C2 prostate tumors in mice and compared with cyto-IL-15 derived from protein purified from inclusion bodies (cyto-IL-15 Gen)." (PMID 34778376, 2021). "In the current study, we aimed to optimize the methodology for production and purification of a modified recombinant human IL-15 and investigate the efficacy of the produced protein in the treatment of prostate tumors." (PMID 34778376, 2021). "This IL-15, when cytotopically modified, showed great efficacy as a monotherapy in prostate tumors in mice further highlighting the potential of IL-15 as a cancer immunotherapy." (PMID 34778376, 2021). "In the TRAMP-C2 prostate tumor model the combination of IL-15 with agonistic anti-CD40 produced additive effects in terms of numbers of TRAMP-C2 tumor specific Spas/SCNC/9H tetramer positive CD8 T cells expressed and tumor responses." (PMID 32508818, 2020). "We also found that IL-15 treatment significantly increased DU145 prostate tumor cell growth in vivo." (PMID 29255466, 2017). "Moreover, in in vivo studies, we have shown induction of cell death and improved mice survival when a membrane-localizing cytotopically modified IL-15 was injected directly into prostate tumors." (PMID 34778376, 2021). "Triple combination of IL-15 with antibodies to PD-L1 and CTLA-4 increased antitumor efficacy and prolonged survival of mice with colon and prostate tumors compared to monotherapies." (PMID 37465665, 2023). "Mice with TRAMP-C1 syngeneic prostate tumors were treated with HBSS (vehicle), cyto-IL-15 or ADU monotherapies or combination of ADU and cyto-IL-15." (PMID 37465665, 2023). "Our study is the first to our knowledge to demonstrate abscopal effects in mice with bilateral prostate tumors treated on a single site with a combination of a STING agonist (ADU-S100) and a cytokine (cyto-IL-15)." (PMID 37465665, 2023). "Our study indicates that IL-12/IL-15 and PD-L1 blocker delivering oHSV-1 vector (VG161) alters the prostate tumor microenvironment and thereby significantly inhibits tumor growth." (PMID 30400822, 2018). "Intratumoral cyto-IL-15 can delay prostate tumor growth and increase survival, however it does not lead to complete regression of tumors even when combined with checkpoint inhibitors." (PMID 37465665, 2023). "Therefore, expansion of Vγ2Vδ2 T cells with IL-15 did not improve immunity against prostate tumors in our humanized mouse model." (PMID 28239463, 2017).